XRCC1 (X-ray repair cross complementing 1)
Diseases named in the same sentence as XRCC1 in open-access papers (continued):
Sharing a sentence is not in itself a finding about the gene and the disease.
cancer (continued). "The expression of XRCC1 in cancer tissues is closely related to the intrinsic genetic phenotype." (PMID 30408066, 2018). "In addition, it has been verified that XRCC1 has a low expression level in many kinds of cancers, and XRCC1 has been proposed to serve as an anti-cancer marker for diagnosis." (PMID 29312615, 2017). "Genetic variations, i.e. polymorphism of DNA repair enzymes and cofactors, 8-oxoguanine DNA glycosylase (OGG1), APE1, X-ray repair cross-complementing protein 1 (XRCC1), XPC, MSH3, RPA-CDK7 among others have been reported to be associated with cancer and neurodegenerative diseases." (PMID 28475635, 2017). "Similarly, XRCC1 with high expression can maintain genomic stability and integrity, and prevent cancer." (PMID 27421136, 2016). "Interestingly, expression of RAD51, a key protein involved in homologous recombination (HR), was suppressed while XRCC1 was up-regulated in oleandrin treated cancer cells." (PMID 27449097, 2016). "We then conducted biological relevance analysis for 33 candidate genes to identify the potential biomarkers, i.e., Interferon regulatory factor (IRF9) and X-ray repair cross-complementing gene (XRCC1), which were involved in the cancer suppression and prevention, respectively." (PMID 27421136, 2016). "This hypothesis is in clear correlation with our detailed analysis of the data, which demonstrated significant changes in the XRCC1 KD cells toward a phenotype detected in cancer cells." (PMID 25800737, 2015). "XRCC1 polymorphisms that reduce BER recruitment to these sites would reduce interference with the nucleotide excision repair pathway, allowing more effective repair of the DNA adduct and increasing cancer cell resistance to the drug." (PMID 25988138, 2015). "DNA damage repair genes JWA, XRCC1 and BRCA1 were associated with clinical outcomes and could convert the response to the cisplatin-based therapy in some carcinomas." (PMID 25925371, 2015). "Although functional studies revealed a possible mechanism for the association of the XRCC1 Arg280His polymorphism with cancer risk, our meta-analysis did not detect a significant association between XRCC1 Arg280His and HNC risk." (PMID 24497981, 2014). "Genetic polymorphisms in XRCC1 gene were not likely to be associated with response to platinum-based chemotherapy in advanced cancer patients." (PMID 24465544, 2014). "Number of cancer individuals reduced when XRCC1 (i.e. SNP2) is omitted from genotype combinations and it indicates that presence XRCC1 polymorphism may increase risk of cancer among population." (PMID 24040168, 2013). "In addition, we also investigated the ability of ATR inhibitors to potentiate cisplatin cytotoxicity in XRCC1 deficient and XRCC1 proficient CHO and human cancer cells." (PMID 23451157, 2013). "Associative studies of malignant tumors of any localization concerning DNA repair gene polymorphisms most often involve XPD nucleotide excision repair genes and XRCC1 base excision repair genes, which are located on the same region of the chromosome (19q13.2–3)." (PMID 22649665, 2010). "It has been suggested that the SNPs of XRCC1 at codon 399 may influence the outcome of cisplatinum-based chemotherapy in some human carcinomas, but the results are also variable." (PMID 19563645, 2009). "In multivariate analysis, the XRCC1 genotypes (model one) and the combined XPD and XRCC1 genotypes (model two) were independently associated with cancer-specific survival in stage T3/T4 patients (RR: 0.0004, 95% CI: not calculated, P=0.02; RR: 0.0003, 95% CI: 0.00–0.53, P=0.0008, respectively)." (PMID 16880786, 2006).
cancer (continued). "However, a comprehensive pan-cancer analysis investigating the prognostic value, immunological functions, and epigenetic associations of XRCC1 remains lacking." (PMID 38217545, 2024). "Furthermore, exploring XRCC1's potential role in tumor immunotherapy and assessing its viability as a therapeutic target will provide valuable insights for the design of tailored cancer therapies and immunotherapy approaches." (PMID 38217545, 2024). "Furthermore, we conducted a survival relevance analysis across multiple cancer types, including progression-free survival (PFS) and disease-specific survival (DSS), to learn the relevance of XRCC1 gene expression levels to the survival prognosis of cancer patients." (PMID 38217545, 2024). "Additionally, our findings are in line with a 2016 systematic review of GxE in all cancer, which identified XRCC1 and VDR as two of the most frequently reported genes with interactions and sun exposure as one of the most commonly reported environmental exposures." (PMID 37537768, 2023). "Second, most included studies about XRCC1 expression and cancer prognosis are from the Chinese population, and most included XRCC1 SNP analysis studies did not provide information on ethnicity; thus, we could not conduct further research on the association in different populations." (PMID 34094945, 2021). "Among the established polymorphisms of the DNA repair genes, the X-ray cross-complementing group 1 (XRCC1) and 8 Oxo guanine DNA-glycosylase 1 (OGG1) polymorphisms have been frequently studied as potentially related with susceptibility to the incidence of several cancers." (PMID 32711416, 2020). "Therefore, XRCC1 plays a crucial role in maintaining genomic stability and preventing cancer." (PMID 30408066, 2018). "We found that the expression of XRCC1 was downregulated in all ccRCC specimens and that the low expression level in ccRCC was strongly related to lymph node metastasis, indicating that XRCC1 might play anti-cancer roles in ccRCC." (PMID 29312615, 2017). "Previous studies based on the data collected post- chemotherapy revealed that high expression of DNA repair gene resulted in resistance to TMZ treatment, which did not contradict with our conclusion that XRCC1 with high expression can decrease the risk of cancer." (PMID 27421136, 2016). "XRCC1 gene might be a valuable genetic marker for chemotherapy in various cancers." (PMID 25925371, 2015). "Considering the importance of XRCC1 in BER pathway and the potential influence of genetic variants in this gene on the repair capacity for DNA damage, a large number of studies were conducted to investigate the association between these three XRCC1 polymorphisms and cancer risk in humans." (PMID 23383237, 2013). "These non-conservative amino acid alterations may alter XRCC1 function and contribute to the risk of cancers." (PMID 23717668, 2013). "XRCC1 mutations have not been identified in human tumors, but XRCC1 single-nucleotide polymorphisms (SNPs) may influence cancer susceptibility by altering the efficacy of DNA repair." (PMID 20705543, 2010). "Finally, we identified the combined Arg194Trp-Arg399Arg genotype of base excision repair gene XRCC1 that was associated with HNSCC and may have an impact on identification of a high-risk cancer population." (PMID 19284666, 2009). "Still, cancer cells appear to be more responsive to elements that activate STAT3, and once STAT3 is activated, XRCC1 gene and protein levels are elevated and impact the cells ’ responses to DNA damage." (PMID 35457130, 2022). "A mouse subcutaneous xenotransplanted tumor model was established, and the expressions of circFLNA, miR-486-3p, XRCC1, CYP1A1, and related genes in the cancer cells and tissues were detected by RT-qPCR, Western blot, or immunohistochemistry." (PMID 33500536, 2022). "Here, we have identified a stress-specific regulatory mechanism for increasing the protein levels of XRCC1, which becomes dysregulated in TNBC and potentially other cancers." (PMID 34067421, 2021).
cancer (continued). "In both cancer cell lines, Twist amplification coincided with an increased expression of DNA damage response (DDR) genes, including PARP1 and XRCC1." (PMID 33920140, 2021). "Among them, circFLNA is a newly discovered gene, and some studies revealed that overexpression of circFLNA, XRCC1, and CYP1A1 can promote survival and malignant development of cancer cells." (PMID 34852712, 2021). "Additionally, we found that XRCC1 was up-regulated in CD133+GBC-SD cells compared with GBC-SD cells, indicating that XRCC1 might be associated with unique biological features of CD133+cancer cells, such as chemo-resistance." (PMID 32426369, 2020). "X-ray repair cross-complementing proteins (XRCC1 and XRCC6), which recruit several DNA damage response proteins and plays key role in DNA repair and cancer progression." (PMID 33251127, 2020). "Previous studies reported that both XRCC1 and CD133+cancer cells are related to tumor drug resistance so that we studied the role of XRCC1 in CD133+GBC-SD cells." (PMID 32426369, 2020). "Their results demonstrate XRCC1 is a vital factor for BBR function in DNA repair and sensitization of cancer cells to anti‐tumoural drugs." (PMID 31338966, 2019). "We artificially expressed XRCC1 in two TNBC, MDA‐MB231 and BT549, and tested the growth of cancer cells treated with BBR." (PMID 31338966, 2019). "Giovanetti and colleagues identified a significant correlation between the Arg399 polymorphism of XRCC1 and a worse response to platinum-based therapeutic regimens, indicating that XRCC1 could be used in PDA to predict response to platinum-based therapies as in other cancers." (PMID 25988138, 2015). "These XRCC1 polymorphisms may affect DNA repair capacity by changing interactions between XRCC1 protein and other proteins in BER pathway, and a large number of studies have focused on the relationship between XRCC1 polymorphisms and development of cancer in humans." (PMID 23717668, 2013). "In this study, we aimed to perform a comprehensive pan-cancer analysis of XRCC1, a pivotal gene in DNA repair, which has not been reported previously." (PMID 38217545, 2024). "Furthermore, the relationship between XRCC1 gene expression levels and MSI status was explored across multiple human cancers." (PMID 38217545, 2024). "Notably, XRCC1 expression was negatively correlated with drug sensitivity in LGG, potentially explaining its classification as a pro-cancer gene." (PMID 38217545, 2024). "In addition, these studies revealed that eIF5A, BRD9, XRCC1, CYP1A1, and CRABP2 were miR-486-3p-regulated cancer-promoting genes in NSCLC cells." (PMID 37508549, 2023). "However, overexpressed XRCC1 and CYP1A1 reversed the inhibitory effect of miR-486-3p mimic on cancer cells and tumors." (PMID 33500536, 2022). "Considering that the expression levels of WNK2, CYP1A1, PAX5, XRCC1, and TGM3 have been reported to be closely related to the development of cancer, we then detected the expression levels of these genes in SK-MES-1 and A549 cells after transfection of circFLNA and miR-486-3p mimic." (PMID 33500536, 2022). "β-lap treatment caused S as well as G2/M arrest in PDA cells, consistent with previous reports indicating that β-lap induced a cell cycle arrest in S phase/ G2/M-phase in diverse cancer cell lines, and XRCC1 knockdown had no detectable effect on cycle." (PMID 34789190, 2021). "In OS analysis, we found no relation between XRCC1 expression and OS in the cancer subgroup or treatment subgroup." (PMID 34094945, 2021). "While APE2 had a significant (α = 0.05) positive correlation with PCNA, APE1, XRCC1, PARP1, Chk1, and Chk2 across all 6 cancer types, groupings of DNA repair and DDR genes were found to be correlated with APE2 in different patterns in different cancer types." (PMID 32111912, 2020).
cancer (continued). "In summary, XRCC1 expression and localization may vary and serve as critical indicators of BER defects in TNBCs and likely other cancers." (PMID 31596905, 2019). "We also propose that the ratio of XRCC1 and ALDH2 levels may serve as a useful prognostic tool in these cancer types." (PMID 30088263, 2018). "Looking at the overall survival rate at 5 years, we found that the XRCC1 mRNA level itself has no prognostic value in any of these cancers." (PMID 30088263, 2018). "We found that the XRCC1 mRNA/ALDH2 mRNA ratio is significantly better at predicting the 5-year overall survival rate for both lung (compare to 3C) and liver (compare to 4C) cancers than ALDH2 levels alone." (PMID 30088263, 2018). "To understand further the relevance of the interplay between XRCC1 and ALDH2 expression in cancer, we investigated whether the profile we observed in most cancers (i.e., low ALDH2 and high XRCC1 mRNA levels) affects patient prognosis." (PMID 30088263, 2018). "Considering that PARP-1 functionally interacts with XRCC1 in BER processes, we performed a gene-gene interaction analysis of the five studies that reported joint effects between PARP1 Val762Ala and XRCC1 Arg399Gln on cancer risks." (PMID 24853559, 2014). "For the cancer phenotypes, the reverse genetics models were enriched in DNA repair functions (p = 2×10−5, FDR p = 0.03) (POLG/FANCI, SLX4/FANCP, XRCC1, BRCA1, FANCA, CHD1L) while the additive model showed enrichment related to chromatid segregation (p = 4×10−6, FDR p = 0.005) (KIF25, PINX1)." (PMID 24349080, 2013). "There are many opinions about influence of XRCC1 (X-ray repair complementing defective repair in Chinese hamster cells 1) and XRCC3 (X-ray repair complementing defective repair in Chinese hamster cells 3) genes on different cancer types." (PMID 23675381, 2013). "The findings that FOXM1B induces DNA repair genes such as XRCC1 and BRCA2 and the fact that most cancers contain genomic instability suggest that activation of DNA repair and genomic instability may not be mutually exclusive in cancer cells." (PMID 19287496, 2009). "Apart from classical BER and SSBR, PARP1, and XRCC1 play a crucial role in the genotoxic response to camptothecin (CPT)-mediated topoisomerase I (Top1) poisoning, and, consequently, combinations of PARP and topoisomerase 1 inhibitors have been tested in clinical cancer therapy." (PMID 35778544, 2023). "Thus, we have identified a novel link between XRCC1 expression and STAT3 activation following exogenous exposures, which could play a critical role in dictating a cancer cell’s response to DNA-damaging agents." (PMID 35457130, 2022). "Interestingly, the ectopic expression of STAT3 in HEK293T did not significantly increase XRCC1 protein content (1.03 ± 0.035), indicating that STAT3 has a less significant role in regulating XRCC1 expression in HEK293T and occurs through a cancer-related, possibly TNBC-specific, mechanism." (PMID 34067421, 2021). "We show that APE2 mRNA expression is positively correlated with PCNA, APE1, XRCC1, PARP1, Chk1, and Chk2 across these 6 tumor tissue types; however, groupings of other DNA repair and DDR genes are correlated with APE2 with different patterns in different cancer types." (PMID 32111912, 2020). "Interestingly, XRCC1 gene expression exhibited a negative correlation with immune cell infiltration levels, except for a positive correlation with M1 and M2 macrophages and monocytes in most cancers." (PMID 38217545, 2024). "The heterozygous genotype TC, combined genotype TC or CC, and allele C of XRCC1 −77T>C may decrease risk of ESCC; however, there was no significantly statistical association after adjusting age, gender, smoking, drinking, and family history of cancer." (PMID 25710005, 2015).
cancer (continued). "Here we show that, in the absence of XRCC1, PARP1 can become excessively engaged on BER intermediates in a manner similar to that induced by anti-cancer PARP1 inhibitors, demonstrating that PARP1 trapping is a threat to normal genome integrity." (PMID 34102106, 2021). "Three out of the six most significant canonical pathways were related to the cancer suppression or prevention, namely Interferon Signaling (IRF9, IFIT3), BER pathway (XRCC1) and DNA Double-Strand Break Repair by Non-Homologous End Joining (XRCC1)." (PMID 27421136, 2016). "STAT3 was not previously identified as a regulator of XRCC1, but the data here demonstrate that STAT3 activation promotes resilience to DNA damage, which likely contributes to chemoresistance or even radiotherapy resistance in cancer cells." (PMID 35457130, 2022). "Therefore, although XRCC1 mRNA levels alone have no prognostic value, low ALDH2 levels show a worse prognosis at 5 years, only in cancers showing a marked difference between ALDH2 and XRCC1 expression." (PMID 30088263, 2018). "In this study, we explored associations between genotypes of base-excision repair genes (PARP1 Val762Ala, APEX1 Asp148Glu, and XRCC1 Arg399Gln) and in vitro BPDE-induced DNA adducts in cultured peripheral blood lymphocytes in 706 cancer-free non-Hispanic white subjects." (PMID 22792228, 2012).